SNORD32A (small nucleolar RNA, C/D box 32A)
Synonyms: U32; U32A; RNU32
Gene: Small nucleolar RNA gene on chromosome 19 (49,489,965 to 49,490,048, forward strand). Ensembl gene ENSG00000201675.
Gene Ontology:
Biological process: RNA processing
Cellular component: nucleolus
Homologues: Orthologues: chimpanzee SNORD33 (100% identical), macaque SNORD33 (98% identical), pig SNORD33 (96% identical), dog SNORD33 (95% identical), mouse Snord32a (87% identical), rabbit SNORD33 (87% identical), rat LOC120100339 (86% identical), tropical clawed frog SNORD33 (61% identical), zebrafish SNORD33 (61% identical), tropical clawed frog SNORD33 (57% identical). Paralogues in human: SNORD32B (89% identical), SNORD33 (69% identical), SNORD33 (48% identical).
Diseases named in the same sentence as SNORD32A in open-access papers:
SNORD32A is named in the same sentence as 5 diseases in open-access papers, as found by Europe PMC text mining. Sharing a sentence is not in itself a finding about the gene and the disease.
SNORD32A shares sentences with these, for which no sentence is quoted: gastric cancer (1 paper); infection (1); laryngotracheitis (1); Mitochondrial myopathy (1); Tumor (1).